APEX1 (apurinic/apyrimidinic endodeoxyribonuclease 1)
Description:
Multifunctional protein that plays a central role in the cellular response to oxidative stress. The two major activities of APEX1 are DNA repair and redox regulation of transcriptional factors. Functions as an apurinic/apyrimidinic (AP) endodeoxyribonuclease in the base excision repair (BER) pathway of DNA lesions induced by oxidative and alkylating agents. Initiates repair of AP sites in DNA by catalyzing hydrolytic incision of the phosphodiester backbone immediately adjacent to the damage, generating a single-strand break with 5'-deoxyribose phosphate and 3'-hydroxyl ends. Also incises at AP sites in the DNA strand of DNA/RNA hybrids, single-stranded DNA regions of R-loop structures, and single-stranded RNA molecules. Operates at switch sites of immunoglobulin (Ig) constant regions where it mediates Ig isotype class switch recombination. Processes AP sites induced by successive action of AICDA and UNG. Generates staggered nicks in opposite DNA strands resulting in the formation of double-strand DNA breaks that are finally resolved via non-homologous end joining repair pathway (By similarity). Has 3'-5' exodeoxyribonuclease activity on mismatched deoxyribonucleotides at the 3' termini of nicked or gapped DNA molecules during short-patch BER. Possesses DNA 3' phosphodiesterase activity capable of removing lesions (such as phosphoglycolate and 8-oxoguanine) blocking the 3' side of DNA strand breaks. Also acts as an endoribonuclease involved in the control of single-stranded RNA metabolism. Plays a role in regulating MYC mRNA turnover by preferentially cleaving in between UA and CA dinucleotides of the MYC coding region determinant (CRD). In association with NMD1, plays a role in the rRNA quality control process during cell cycle progression. Acts as a loading factor for POLB onto non-incised AP sites in DNA and stimulates the 5'-terminal deoxyribose 5'-phosphate (dRp) excision activity of POLB. Exerts reversible nuclear redox activity to regulate DNA binding affinity and transcriptional activity of transcriptional factors by controlling the redox status of their DNA-binding domain, such as the FOS/JUN AP-1 complex after exposure to IR. Involved in calcium-dependent down-regulation of parathyroid hormone (PTH) expression by binding to negative calcium response elements (nCaREs). Together with HNRNPL or the dimer XRCC5/XRCC6, associates with nCaRE, acting as an activator of transcriptional repression. May also play a role in the epigenetic regulation of gene expression by participating in DNA demethylation. Stimulates the YBX1-mediated MDR1 promoter activity, when acetylated at Lys-6 and Lys-7, leading to drug resistance. Plays a role in protection from granzyme-mediated cellular repair leading to cell death. Binds DNA and RNA. Associates, together with YBX1, on the MDR1 promoter. Together with NPM1, associates with rRNA.
Synonyms: APEN; APE-1; REF-1; APE; APE1; APEX; APX; HAP1; REF1
Tractability: Small molecule: a drug acting on it is in phase 2 or 3 trials; a structure with a bound ligand is known; a high-quality ligand is known; it has a binding pocket of medium quality; it belongs to a druggable protein family. PROTAC: UniProt records ubiquitination sites on it; ubiquitination databases record sites on it; its protein half-life has been measured; a small molecule that binds it is known.
Target class: Enzyme
Chemical probes: ML199, TANSHINONE IIA
Gene: Protein-coding gene on chromosome 14 (20,454,525 to 20,457,779, forward strand). Ensembl gene ENSG00000100823.
Subcellular location: Nucleus; Nucleus, nucleolus; Nucleus speckle; Endoplasmic reticulum; Cytoplasm; Mitochondrion (DNA repair nuclease/redox regulator APEX1, mitochondrial)
Subcellular location (Human Protein Atlas): Nucleoplasm; Centrosome
Pathways (Reactome):
DNA Repair: Abasic sugar-phosphate removal via the single-nucleotide replacement pathway; Displacement of DNA glycosylase by APEX1; PCNA-Dependent Long Patch Base Excision Repair; POLB-Dependent Long Patch Base Excision Repair; Resolution of AP sites via the multiple-nucleotide patch replacement pathway; Resolution of Abasic Sites (AP sites)
Gene Ontology:
Molecular function: 3'-5' exonuclease activity; 3'-5'-DNA exonuclease activity; chromatin DNA binding; class II DNA-(apurinic or apyrimidinic site) endonuclease activity; damaged DNA binding; deoxyribonuclease (pyrimidine dimer) activity; DNA binding; DNA-(abasic site) binding; DNA-(apurinic or apyrimidinic site) endonuclease activity; double-stranded DNA 3'-5' DNA exonuclease activity; double-stranded DNA exodeoxyribonuclease activity; double-stranded telomeric DNA binding; endonuclease activity; metal ion binding; oxidoreductase activity; phosphodiesterase activity, acting on 3'-phosphoglycolate-terminated DNA strands; phosphoric diester hydrolase activity; protein binding; RNA binding; transcription coactivator activity; DNA endonuclease activity; phosphodiesterase I activity; RNA-DNA hybrid ribonuclease activity; transcription corepressor activity; uracil DNA N-glycosylase activity; and 2 more
Biological process: base-excision repair; DNA catabolic process; DNA repair; positive regulation of gene expression via chromosomal CpG island demethylation; positive regulation of transcription by RNA polymerase II; regulation of apoptotic process; regulation of mRNA stability; telomere maintenance; telomere maintenance via base-excision repair; base-excision repair, gap-filling; granzyme-mediated apoptotic signaling pathway; negative regulation of DNA-templated transcription
Cellular component: cytoplasm; mitochondrion; nuclear speck; nucleolus; nucleoplasm; nucleus; perinuclear region of cytoplasm; chromatin; chromosome, telomeric region; endoplasmic reticulum; ribosome
Genetic constraint (gnomAD): Loss-of-function variants: 32 observed, 35.07 expected, observed/expected ratio (o/e) 0.91, 90% interval 0.69 to 1.23. The upper end of that interval is the gene's LOEUF score, 1.23, which puts it in group 5 of 6, group 1 being the genes least tolerant of losing a copy. Missense variants: 442 observed, 418.42 expected, observed/expected ratio (o/e) 1.06, 90% interval 0.98 to 1.14. Synonymous variants: 175 observed, 167.09 expected, observed/expected ratio (o/e) 1.05, 90% interval 0.93 to 1.19.
Homologues: Orthologues: chimpanzee APEX1 (99% identical), macaque APEX1 (98% identical), dog APEX1 (95% identical), rabbit APEX1 (95% identical), guinea pig APEX1 (94% identical), mouse Apex1 (94% identical), pig APEX1 (94% identical), rat Apex1 (90% identical), tropical clawed frog apex1 (66% identical), zebrafish apex1 (66% identical), Drosophila melanogaster Rrp1 (53% identical), Caenorhabditis elegans exo-3 (39% identical). Paralogues in human: APEX2 (24% identical).
Diseases named in the same sentence as APEX1 in open-access papers:
APEX1 is named in the same sentence as 215 diseases in open-access papers, as found by Europe PMC text mining. Sharing a sentence is not in itself a finding about the gene and the disease. The quoted sentences say what the papers report.
lung cancer (68 papers, 2008 to 2024). A malignant neoplasm involving the lung. "In lung cancer patients homozygous for the APEX1 D148E minor allele, overall survival was reported to be prolonged rather than reduced, again demonstrating differences between cancer types." (PMID 34708297, 2022). "Accumulating evidence indicates that elevated and ectopic expression of APEX1 in tumor tissue is closely linked to a poor prognosis for lung cancer." (PMID 35780128, 2022). "The overexpression of the DNA repair protein apurinic/apyrimidinic endodeoxyribonuclease 1 (APE1) is an important cause of poor chemotherapeutic response in lung cancer and its involvement in onco-miRNAs biogenesis has been recently described." (PMID 35876890, 2022). "As previously reported for lung cancer, the association was dependent upon the coexistent APEX1 D148E genotype." (PMID 34708297, 2022). "The elevated levels of APEX1 have been reported in several cancers, including lung cancer, and also to be associated with resistance to chemotherapy and radiotherapy in some cancers." (PMID 32983988, 2020). "Variants in the APEX1 gene are found to associate with susceptibility to several cancers, including cervical cancer, glioblastoma, bladder cancer, and lung cancer." (PMID 31341530, 2019). "A meta-analysis of 15 studies involving 4,932 lung cancer patients and 6,555 cancer-free controls found that in an Asian population, carriers of APEX1 D148E exhibited an increased risk of developing lung cancer." (PMID 29662108, 2018). "Taking lung cancer as an example, the APEX1 148Glu allele was a risk-conferring factor in Caucasians, but a risk-reducing factor in Asians." (PMID 24349526, 2013). "Recently, we reported that genetic polymorphisms of APEX1 in DNA repair pathways contributed to lung cancer susceptibility, which was dependent on smoking status." (PMID 23443124, 2012). "In contrast, another study reported a protective role of APEX1 Glu allele against lung cancer risk." (PMID 36287252, 2023). "Finally, more functional researches will be performed in futures, which are important to confirm the biological relevance of APEX1-associated AS in lung cancer." (PMID 35780128, 2022). "Previous in vitro promoter assay has detected that the rs1760944 T allele significantly lowered promoter activity than that of the G allele, which indicated the variant allele (T) may be associated with a low transcriptional activity of the APEX1 in lung cancer cells." (PMID 28827732, 2017). "CPM can significantly inhibit cell viability, ROS production, intracellular pH, migration in hypoxic lung cancer cells, and angiogenesis of HUVECs under hypoxia through the inhibition of APEX1/HIF-1α interaction." (PMID 39175079, 2024). "We also investigated the potential risk of lung cancer development among PAHs exposed workers with emphasis on the role of A1AT mutation and APEX1 gene polymorphisms." (PMID 36287252, 2023). "have found that APEX1 and Nrf2 physically interacts, which suggests that APEX1 mediates Nrf2 activation in lung cancer cells." (PMID 35311089, 2022). "Our research has analogous findings that APEX1 was cancer-promoting and that AS of cancer-related genes had a critical impact on lung cancer cell biology." (PMID 35780128, 2022). "It has been also reported that a personal low baseline DNA repair score, composed of the BER-associated enzymatic activities of APEX1, MPG and OGG1 (all of which act primarily on oxidative DNA damage) consists of a strong risk factor for lung cancer." (PMID 35740268, 2022). "For example, cephalomannine was found to exert inhibitory effects in hypoxic lung cancer cells via the inhibition of the interaction between apurinic/apyrimidinic endonuclease-1 (APEX1) and hypoxic-induced factor-1α (HIF-1α)." (PMID 36500375, 2022). "Photoirradiation of a lung cancer therapy induces the mitochondrial translocation of APEX1 to control mitochondrial transcription activity by mitochondrial transcription factor A as a redox regulation." (PMID 31375000, 2019).
lung cancer (continued). "Moreover, it also investigates lung cancer risk among PAHs exposed workers with emphasis on the role of A1AT mutation and APEX1 gene polymorphisms on their susceptibility to lung cancer development." (PMID 36287252, 2023). "Our results further supported the concept that targeting differential AS related to APEX1 may be a means by which to reduce cell proliferation and induce apoptosis of tumors in patients with lung cancer." (PMID 35780128, 2022). "Furthermore, we found that APEX1 activated the TGFβ/SAMD3 signal pathway by promoting lung cancer cells proliferation, which may activate or repress their target gene promoters." (PMID 35780128, 2022). "In this study, we assessed the OGG1 Ser326Cys, MUTYH Gln324His, APEX1 Asp148Glu, XRCC1 Arg399Gln, and XRCC3 Thr241Met gene polymorphisms that may influence DNA repair capacity and their association with the overall survival of lung cancer patients." (PMID 23443124, 2012). "We focused on OGG1 Ser326Cys, MUTYH Gln324His, APEX1 Asp148Glu, XRCC1 Arg399Gln, and XRCC3 Thr241Met and examined the relationship between the different genotypes and survival of Japanese lung cancer patients." (PMID 23443124, 2012). "Furthermore, knockdown or inhibitor of APEX1 suppresses migration and invasion and promotes EMT through interaction with sirtuin-1 (SirT1) in non–small cell lung cancer (NSCLC)." (PMID 31454981, 2019). "However, there have been no previous reports on OGG1, MUTYH, and APEX1 with regard to survival in lung cancer." (PMID 23443124, 2012).
breast carcinoma (58 papers, 2009 to 2025). "For example, APEX1 expression is inversely associated with survival among patients with breast cancer, gastric cancer and prostate cancer." (PMID 36205565, 2022). "In APEX1 rs3136817, we found that the heterozygous TC genotype and the C allele were associated with breast cancer risk (adjusted OR = 0.670, 95% CI: 0.513 - 0.873, P = 0.003; adjusted OR = 0.729, 95% CI: 0.576 - 0.923, P = 0.009, respectively)." (PMID 29720094, 2018). "To provide the most comprehensive assessment of the associations between OGG1 Ser326Cys and APEX1 Asp148Glu polymorphisms and breast cancer risk, we performed an updated meta-analysis of all available studies." (PMID 24893568, 2014). "To provide the most comprehensive assessment of the association between OGG1 Ser326Cys and APEX1 Asp148Glu polymorphisms and breast cancer risk, we performed this meta-analysis of all available studies." (PMID 24893568, 2014). "Based on our search criteria, 24 studies relevant to the role of OGG1 Ser326Cys and APEX1 Asp148Glu polymorphisms on breast cancer susceptibility were identified." (PMID 24893568, 2014). "We therefore in this study aimed to assess the potential interactions of seven common polymorphisms from five DNA repair genes (XRCC1, XRCC2, XRCC3, XPA and APEX1) in association with breast cancer among Han Chinese women." (PMID 24642895, 2014). "Many epidemiological studies have been performed to evaluate the role of OGG1 Ser326Cys and APEX1 Asp148Glu polymorphisms on breast cancer risk; however, the results remained conflicting and contradictory." (PMID 24893568, 2014). "In summary, our data provide clear evidence that the rs3136817 polymorphism in APEX1 and a corresponding haplotype may be involved in breast cancer risk in the Han women of Northwest China." (PMID 29720094, 2018). "However, a few reports which were different from our results also indicated that breast cancer risk was significantly associated with APEX1 rs1130409 in North Indian, Korean and Caucasian women." (PMID 29720094, 2018). "A total of 518 patients with histopathologically confirmed breast cancer and 921 region- and age-matched cancer-free controls were genotyped for the APEX1 polymorphisms rs3136817 and rs1130409 and the OGG1 polymorphisms rs1052133 and rs2072668 using a QuantStudioTM 12 K Flex Real-Time PCR System." (PMID 29720094, 2018). "The main effect model of rs3136817 performed best, which implies that the APEX1 rs3136817 polymorphism is a powerful risk factor and may play an important role in the interaction with other SNPs in affecting breast cancer development, either synergistically or antagonistically." (PMID 29720094, 2018). "Consequently, we infer that the APEX1 CT haplotype may be involved in decreasing the risk of breast cancer." (PMID 29720094, 2018). "Wang T., Wang H., Yang S., Guo H., Zhang B., Guo H., Wang L.,Zhu G., Zhang Y., Zhou H., Zhang X., Li H., Su H. Associationof APEX1 and OGG1 gene polymorphisms with breast cancer riskamong Han women in the Gansu Province of China." (PMID 39027127, 2024). "We estimated the relationship between APEX1 and OGG1 gene polymorphisms and breast cancer risk among 1430 Han women of Northwest China in this experiment using a tag SNP-based study." (PMID 29720094, 2018). "The current study aimed to estimate the association of APEX1 and OGG1 polymorphisms with the risk of breast cancer development." (PMID 29720094, 2018). "Comparing only smoker groups, the frequencies of XRCC1, APEX1, XPD, CYP2A6*2 and CYP2A6*9 genetic polymorphisms were similar in both controls and breast cancer patients." (PMID 27754415, 2016). "Of these, two SNP pairs (APEX1-rs1130409 *RPAP1-rs2297381 and MLH1-rs1799977 *MDM2-rs769412) showed the strongest statistical association with breast cancer (P<7.3×10−3), with modest FDR values of 0.30 and 0.49, respectively." (PMID 23755158, 2014).
breast carcinoma (continued). "The present work aimed to investigate whether APEX1 and OGG1 gene polymorphisms (frequency ≥ 5%) exert any synergistic effects on breast cancer risk." (PMID 29720094, 2018). "This research is the latest report showing that an APEX1 rs3136817 heterozygous genotype may have a positive influence on DNA repair capacity in patients with breast cancer and thus may have a potential protective effect for Chinese Han women." (PMID 29720094, 2018). "To date, many epidemiological studies have been performed to evaluate the association between OGG1 Ser326Cys and APEX1 Asp148Glu polymorphisms and breast cancer risk, but the results remain conflicting rather than conclusive." (PMID 24893568, 2014). "The exact relationship between genetic polymorphisms of OGG1 Ser326Cys and APEX1 Asp148Glu and breast cancer susceptibility has not been entirely established." (PMID 24893568, 2014). "However, our data did not support a significant association between APEX1 Asp148Glu polymorphism and breast cancer risk both in the pooled analysis and stratified analyses." (PMID 24893568, 2014). "MDR analysis also showed a close interaction and mutual enhancement of effects between the APEX1 and SOD2 loci and the independence of the effects of these loci from the CAT locus in the formation of luminal B subtype breast cancer." (PMID 39027127, 2024). "Similar to our findings, the interaction of APEX1 and NPM1 has also been reported by previous research in breast cancer and this interaction contributes to drug resistance in triple negative breast cancer." (PMID 38360860, 2024). "For instance, APEX1 overexpression is positively correlated with cancer progression, whereas NPM1 is known as a poor prognostic factor in breast cancer patients." (PMID 36672349, 2023). "Likewise, germline variants in APEX1 (14th by MUFFINN yet below 13,000th by the gene-centric methods in head and neck squamous cell carcinoma (HNSC) samples) is known to increase the risk of breast cancer development by contributing apurinic/apyrimidinic (AP) site accumulation in DNA." (PMID 27333808, 2016). "We observed two two-way SNP-SNP interactions (APEX1-rs1130409 and RPAP1-rs2297381; MLH1-rs1799977 and MDM2-rs769412) in logistic regression that conferred elevated risks for breast cancer (Pinteraction<7.3×10−3)." (PMID 23755158, 2014). "Associations of polymorphisms in the hOGG1 (rs1052133), APEX1 (rs1130409), XPD (rs13181), SOD2 (rs4880), and CAT (rs1001179) genes were studied in 313 nonsmoking postmenopausal patients with luminal B subtype breast cancer." (PMID 39027127, 2024). "Except for APEX1-rs1130409, the SNPs participating in SNP-SNP interactions also showed weak single-locus effects (both allelic and genotypic) for breast cancer, independent of BMI." (PMID 23755158, 2014).